MTOR (mechanistic target of rapamycin kinase)
Diseases named in the same sentence as MTOR in open-access papers (continued):
Sharing a sentence is not in itself a finding about the gene and the disease.
cancer (continued). "Altogether, these findings highlight the potentialof four novel bioflavonoid compounds exhibiting a sense of chiralityas promising candidates for the rational design of new cancer therapeuticstargeting PI3Kα and mTOR." (PMID 41048819, 2025). "MAPK signaling, Wnt signaling, mTOR signaling, and pathways in cancer were the only overrepresented pathways common to males and females in endothelial cells." (PMID 41310161, 2025). "AOS‐SO4 blocks the MEK1/ERK/mTOR signaling pathway, which is involved in various human malignant tumors and promotes angiogenesis and cell growth." (PMID 40567251, 2025). "Mechanistically, it was reported that BGN secreted by cancer cells was elicited by Akt/mTOR and MNK/eIF4E pathways and offered the immunosuppressive microenvironment to cancer cells by recruiting suppressive myeloid cells." (PMID 40524231, 2025). ": Although targeting HDACs to treat cancers has been established, targeting both mTOR and HDACs has been shown to have promising results." (PMID 41286527, 2025). "Rapamycin has been widely recognized for its role as an mTOR inhibitor, which has led to its use in cancer therapy, particularly for cancers driven by mTOR signalling." (PMID 39762538, 2025). "Along with its derivative everolimus, sirolimus belongs to the class of mammalian target of rapamycin (mTOR) inhibitors, which are increasingly employed in cancer treatment." (PMID 40788512, 2025). "Studies have shown that inhibition of mTOR can induce a dormancy-like state in various cancer cell lines, and its modulation is critical for the transition to and maintenance of a quiescent state." (PMID 40732251, 2025). "Several genes responsible for cancer cell metabolism, proliferation, and invasion regulated by mTOR signalling have been described." (PMID 39941741, 2025). "PLOD1 drives proliferation, migration, invasion, and therapy resistance in cancers by modulating pathways like β-catenin, NF-κB, and Akt/mTOR." (PMID 41373732, 2025). "This activation leads to the AKT/mTOR signaling pathway being turned on in PCa cells, thus promoting cancer progression." (PMID 40867281, 2025). "mTOR, a central regulator in cell growth and survival, plays a pivotal role in various human cancers." (PMID 39542458, 2025). "mTOR inhibitors, such as everolimus and temsirolimus, are used in the treatment of various cancers, including renal cell carcinoma and BC." (PMID 40080721, 2025). "Insulin resistance leads to increased insulin-like growth factor 1 (IGF-1), which activates cancer-promoting pathways like AKT/mTOR/PI3K and ERK/RAS/MAPK, supporting tumor growth and survival." (PMID 40507982, 2025). "Mammalian target of rapamycin (mTOR) is an important kinase downstream of PI3K‐AKT that regulates cancer cell angiogenesis, growth, proliferation and survival." (PMID 39907159, 2025). "A key driver of tumor progression is the constitutive activation of the mTOR (mechanistic target of rapamycin) signaling pathway, observed in multiple cancer types." (PMID 40869090, 2025). "Meanwhile, the BCAAs can contribute to cancer progression probably by the modulation of the mTOR activity." (PMID 41347062, 2025). "In our cohort of patients with PCa, AR, FOXA1, MTOR, and MDM2 showed the highest rate of novel and pathogenic mutations, with 7, 3, 3, and 2, respectively, evidencing their relevance in this type of cancer." (PMID 41009328, 2025). "Hyperactivation of the Akt/mTOR/c-Myc signaling pathway in cancer cells increases the expression of GLUT4, which in turn augments the ability of multidrug resistant cells to rapidly transport and consume glucose through glycolysis." (PMID 40612109, 2025). "Gold nanoparticles (AuNPs) impede the phosphorylation of AKT and mTOR, resulting in the induction of autophagy in cancer cells." (PMID 40076496, 2025). "Current FDA-approved PI3K/Akt/mTOR inhibitors are limited to cancer therapy, largely due to their off-target effects and toxicities." (PMID 39821606, 2025).
cancer (continued). "mTOR is a highly conserved serine/threonine protein kinase that plays a crucial role in tumorigenesis and cancer development through the PI3K/AKT/mTOR signaling pathway." (PMID 39948481, 2025). "Several molecular pathways, including the PI3K/AKT/mTOR pathway, are known to be aberrantly activated in cancers." (PMID 40676293, 2025). "Glucose restriction is also known to suppress energy-dependent pathways, including PI3K-Akt and mTOR signalling in cancer cells." (PMID 41013205, 2025). "Proteome analysis revealed that SLC25A20 knockdown reduced cancer cell growth significantly due to inactivation of mTOR via decreased ATP production, ultimately leading to cell death." (PMID 40521210, 2025). "In order to improve the regulation on PI3K/AKT/mTOR axis, the studies can focus on the combination of phytochemicals and small molecules in cancer therapy." (PMID 40740483, 2025). "In vitro and in vivo studies indicate that quercetin stimulates autophagy by inhibiting the Akt/mTOR pathway, elucidating a mechanism by which quercetin can restrict tumor development and enhance cancer cell viability under hypoxic settings." (PMID 40004215, 2025). "mTOR is often hyperactivated in cancer, leading to increased protein synthesis, cell growth, and angiogenesis, all essential for tumor progression." (PMID 40041495, 2025). "Inhibition of mTOR signaling has been shown to sensitize cancer cells to apoptosis and enhance the efficacy of other targeted therapies." (PMID 40592982, 2025). "Cancer cells, which often rely on mTOR hyperactivation to support their rapid proliferation, are particularly vulnerable to mTOR inhibition induced by fasting." (PMID 39940361, 2025). "In contrast, the regulation of CNV cancer cells by the PI3K/AKT/mTOR signaling pathway appeared to have a relatively smaller impact compared with malignant epithelial cells." (PMID 40244296, 2025). "PCNA mRNA levels were altered in across cancers andassociated with altered cancer signaling networks constituting Wnt,Hippo, and mTOR pathways." (PMID 40657100, 2025). "The well-known comprehension is that the PI3K/Akt/mTOR pathway plays a crucial role in cancer growth and tumor proliferation." (PMID 40538534, 2025). "It includes various immune cells and important signaling pathways, such as TGF-β, NF-κB, and PI3K/AKT/mTOR, which help the cancer survive and grow." (PMID 40075635, 2025). "Intriguingly, LARP1, a keystone in the mTOR pathway's influence on cancer metastasis, caught our attention as a potential interactor with TBG." (PMID 39786317, 2025). "mTOR plays a role in the formation of some drug-resistant cancers in digestive tract, respiratory, kidney, and skin." (PMID 40943615, 2025). "This distinction underscores the promise of mTOR inhibitors in non-cancer applications and highlights the importance of further mechanistic studies and validation." (PMID 40299431, 2025). "HK can be activated through the PI3K/Akt/mTOR signaling and other survival pathways in cancer cells, resulting in MDR." (PMID 40612109, 2025). "The chaperonin CCT is being explored as a diagnostic and therapeutic target in many cancers, including GBM, owing to its involvement in key oncogenic signaling pathways such as Wnt, VEGF, EGFR, and PI3K/AKT/mTOR." (PMID 41516249, 2025). "Although mTOR inhibitors are effective in the treatment of benign tumor with mTOR activation, their efficacy is limited in malignant tumor, largely due to their cytostatic nature." (PMID 39863613, 2025). "HFD increases FAO, which in turn increases ATP and, consequently, mTOR activation, this drives cancer growth." (PMID 40521210, 2025).
cancer (continued). "The simultaneous regulation of PI3K/AKT/mTOR signaling and autophagy is under investigation to address resistance mechanisms and enhance therapeutic efficacy in cancer treatment." (PMID 40076496, 2025). "The PI3K/AKT/mTOR signaling pathway plays a pivotal role in regulating growth in both normal and cancer cells." (PMID 39895626, 2025). "In cancer, the hyperactivation of the PI3K/AKT/mTOR pathway inhibits autophagy, facilitating tumor formation; conversely, in certain instances, the activity of autophagy aids cancer cells in enduring therapy-induced stress." (PMID 40076496, 2025). "This inhibition stimulates AMPK, suppressing mTOR and facilitating autophagy-induced cancer cell death." (PMID 40076496, 2025). "Previous studies have shown that the PI3K/AKT/mTOR pathway relates to drug resistance and cancer development in various cancers." (PMID 40852728, 2025). "When hyperactivated, mTOR signaling promotes cell proliferation and metabolism that aids in tumor progression; mTOR signaling is enhanced in various types of cancer, and inhibition of this pathway is a promising therapeutic target." (PMID 40066850, 2025). "It has been found that several pharmaceuticals, both natural and artificial, are effective in inhibiting mTOR and regulating the growth of cancer." (PMID 40717210, 2025). "The significant role of the PI3K/AKT/mTOR pathway in the pathogenesis of many cancers means that it is increasingly being targeted in the development of novel oncological therapies." (PMID 39254838, 2025). "This review study discusses the effects of plant bioactive compounds on altering mTOR signaling and their possible use in cancer treatment." (PMID 40717210, 2025). "AMPK is verified to be a promoter of autophagy, and it inhibits mTOR activity to promote autophagy in cancer progression." (PMID 39861714, 2025). "Research on the use of mTOR inhibitors in conjunction with tailored nanoparticles to treat certain cancers is essential." (PMID 40717210, 2025). "Elevated expression of proteins and phosphoproteins of downstream of EGFR/ERBB in cluster #3 and #1 suggests EGFR/ERBB, SRC, c-RAF/MAPK, and PI3K/AKT/mTOR/RICTOR signaling as a major tumor-promoting circuits of these cancers." (PMID 40011822, 2025). "High IRS4 levels in cancer cells activate the PI3K/Akt/mTOR pathway, and experimental knockdown of IRS4 significantly decreases pathway proteins, suggesting its potential regulation in ULM." (PMID 40867239, 2025). "For instance, rapamycin activates autophagy via the mTOR (mammalian target of rapamycin) pathway and has been shown to exert beneficial effects in cardiovascular diseases as well as in cancer treatment." (PMID 40430490, 2025). "Everolimus suppresses PI3K/AKT/mTOR by blocking the mTOR which promotes cancer cell metastasis and proliferation." (PMID 40374533, 2025). "There is a clear need for new drugs targeting previously unexplored aspects of cancer biology, such as mitotic kinesins, Aurora kinases, and mTOR inhibitors." (PMID 40272602, 2025). "One treatment strategy is targeting the mammalian target of rapamycin (mTOR) pathway to sensitize resistant cancer cells." (PMID 40385549, 2025). "The mTOR signalling pathway is commonly overactive in cancer, leading to uncontrolled cell proliferation and metabolic rewiring, making it an attractive target for treatment." (PMID 41471075, 2025). "ISO inhibits the activity of the PI3K/AKT/mTOR signaling pathway through multiple mechanisms, thereby inhibiting the proliferation, migration, and invasion of a wide range of cancer cells." (PMID 40507124, 2025). "The PI3K/AKT/mTOR pathway serves as a critical signaling nexus in cancer, with AKT acting as a central regulator of tumor cell proliferation, survival, metabolism, and therapy resistance." (PMID 40746599, 2025). "The dysregulation of the PI3K/AKT/mTOR pathway is recognized as a key driver of cancer growth and progression." (PMID 40717210, 2025).
cancer (continued). "Rapamycin analogs (rapalogs) have been approved for cancer treatment, and many mTOR inhibitors with different mechanisms of action, such as everolimus, temsirolimus, and AZD8055, have been developed." (PMID 40563640, 2025). "The PI3K/Akt/mTOR pathway is crucial for regulating the cell cycle, proliferation, apoptosis, and metabolism, and is activated in many cancers due to dysregulated receptor tyrosine kinases (RTK)." (PMID 40387965, 2025). "Studies have shown that the abnormal activation of the mTOR signaling pathway is closely related to the occurrence and development of tumors in various cancers." (PMID 40573188, 2025). "The results showed that the scores of the WNT and NOTCH signaling pathways in CNV cancer cells were lower than those of the PI3K/AKT/mTOR signaling pathway." (PMID 40244296, 2025). "Prolonged stress can dysregulate the hypothalamic-pituitary-adrenal (HPA) axis and elevate cortisol levels, fostering a systemic environment conducive to cancer progression through distinct regulatory pathways such as the PI3K/AKT/mTOR pathway." (PMID 40887471, 2025). "These preclinical studies show the broad application prospects of PI3K/AKT/mTOR inhibitors in cancer." (PMID 40725100, 2025). "OPCML–RTK interactions are documented in other cancers: mapping them in GBM would connect the surface biochemistry to the AKT/mTOR readouts observed here." (PMID 41561740, 2025). "mTOR signaling, a central regulator of cell growth and metabolism, plays a dual role in cancer progression by both activating and being activated by HIF‐1." (PMID 39969135, 2025). "In the case of the mTOR pathway, its inhibition has emerged as a promising therapeutic strategy by promoting apoptosis in cancer cells and overcoming resistance towards treatments." (PMID 40407951, 2025). "Our study aimed to evaluate the possible relationships between signaling pathways involved in cancer development and the mTOR molecule using bioinformatics tools." (PMID 41300706, 2025). "This provides a rationale for targeting lipid metabolic regulators such as SREBP1 and SCD1 in PI3K/AKT/mTOR‐mutant cancers, thereby overcoming intrinsic resistance to ferroptosis." (PMID 40740483, 2025). "There are ongoing clinical trials investigating the combination of BGT226 (or other PI3K/mTOR inhibitors) with HSP90 inhibitors like STA9090 in other cancers, but data on safety, efficacy, and optimal dosing regimens are still emerging." (PMID 41282100, 2025). "By blocking the PI3 K/Akt/mTOR axis and reducing cancer stem cell indicators such as ALDH, piperine and doxorubicin in combination helps to overcome chemoresistance in triple-negative breast cancer (TNBC)." (PMID 40676293, 2025). "The present review provided a comprehensive discussion of the function of PI3K/AKT/mTOR axis in cancer." (PMID 40740483, 2025). "Cancer cells can exploit this mechanism to counteract the anti-proliferative effects of MTOR-dependent anticancer drugs, including rapamycin and its analogs CCI-779 and RAD001." (PMID 39988732, 2025). "LAT1 supplies cancer cells with EAAs necessary for protein synthesis and promotes cancer growth through the activation of the mammalian target of rapamycin (mTOR) pathway." (PMID 40923294, 2025). "Enhanced BCAA catabolism promotes cancer cell proliferation through mTOR signaling, presenting potential therapeutic value." (PMID 40066850, 2025). "CK inhibits the PI3K/mTOR/p70S6K1 signaling pathway in cancer cells and reduces the expression of MMP." (PMID 40422575, 2025). "Numerous studies have highlighted the potential of natural products to target the PI3K-Akt-mTOR signaling pathway for cancer prevention and therapy." (PMID 40806360, 2025).
cancer (continued). "High glucose levels activate PI3K/AKT/mTOR signaling, a critical pathway in cancer cell survival and proliferation." (PMID 40387523, 2025). "mTOR was chosen for structural docking research because of its pivotal involvement in cancer development and significant enrichment in KEGG pathways among the hub proteins." (PMID 41465766, 2025). "Rapamycin, an mTOR signaling pathway inhibitor, and other rapalogs can directly target precancerous cells and delay organismal aging, thus slowing cancer development." (PMID 40115255, 2025). "The findings of this study indicate that the mTOR signaling pathway substantially contributes to cancer etiopathogenesis and represents a tractable target for therapeutic intervention." (PMID 41300706, 2025). "The drug's potential anti-cancer capabilities were investigated, as mTOR is important in cell growth and proliferation." (PMID 40933955, 2025). "To identify potential effectors of this phenotype, we examined the mTOR pathway, a well-established driver of translation in cancer, which is known to phosphorylate 4E-BP1 and ribosomal protein S6 to enhance translation efficiency." (PMID 40805278, 2025). "silymarin-functionalized selenium nanoparticles (Si-SeNPs) induce autophagy and exert cytotoxicity by inhibiting the PI3K/AKT/mTOR pathway, leading to apoptosis and ultimately promoting cancer cell death." (PMID 40066330, 2025). "Cancer cells can activate mTOR due to increased ATP levels, which they use to produce new biomolecules that support cell regrowth." (PMID 40848971, 2025). "Activation of AGC kinase members such as serum/glucocorticoid-regulated kinase 1 (SGK1), Akt, and PKC is regulated by mTOR, and these enzymes are relevant in case of apoptosis, cancer, and diabetes." (PMID 40148800, 2025). "As a major downstream effector of AKT, mTOR is closely related to the biological behavior of malignant neoplasms." (PMID 40541935, 2025). "Aberrations in the PIK3R1 gene are associated with poor prognosis in cancer; available data underscore the significant role of PIK3R1 mutations in mediating tumorigenesis by promoting the signaling of the PI3K/AKT/mTOR pathway." (PMID 40657399, 2025). "RNF167 targets CASTOR1 for proteasomal degradation and activates mTOR signaling to promote cancer progression." (PMID 39851497, 2025). "Specifically, fisetin was shown to have anti-cancer activity by modulating PI3K/AKT/mTOR pathway in various types of cancer." (PMID 41180483, 2025). "HIV’s p17 activates the PI3K/Akt/mTOR pathway, which is critical for the development and malignant progression of several cancers." (PMID 40563634, 2025). "NVP-BEZ235 can effectively reverse the hyper-activation of the PI3K/AKT/mTOR signaling, resulting in the antitumor activities in a broad range of cancers." (PMID 40771929, 2025). "Various mTOR-targeted drugs have been developed, including different rapalogs, to interfere with cancer cell metabolism; these drugs are also explored as part of anti-aging strategies." (PMID 39963130, 2025). "Nanoparticles have emerged as an effective tool for the precise control of the PI3K/AKT/mTOR pathway, significantly contributing to cancer therapy." (PMID 40076496, 2025). "This drug belongs to a class of drugs called PI3K/mTOR inhibitors, meaning it works by blocking specific proteins involved in the growth and survival of cancer cells." (PMID 41157256, 2025). "Given its frequent activation in human cancer, the PI3K/AKT/mTOR pathway has become an attractive target for cancer therapy." (PMID 41180483, 2025). "Several factors contribute to the limitations of mTOR inhibitors in cancer treatment, including tumor heterogeneity, adaptive resistance mechanisms, and feedback activation of alternative signaling pathways." (PMID 40299431, 2025). "As a core regulator of cellular metabolism, mTOR modulates the reprogram of glucose and lipid metabolism, which provides nutrition for the rapid proliferation and survival of cancer cells." (PMID 40315213, 2025).